FUZ (fuzzy planar cell polarity protein)
Description:
Probable planar cell polarity effector involved in cilium biogenesis. May regulate protein and membrane transport to the cilium. Proposed to function as core component of the CPLANE (ciliogenesis and planar polarity effectors) complex involved in the recruitment of peripheral IFT-A proteins to basal bodies. May regulate the morphogenesis of hair follicles which depends on functional primary cilia. Binds phosphatidylinositol 3-phosphate with highest affinity, followed by phosphatidylinositol 4-phosphate and phosphatidylinositol 5-phosphate (By similarity).
Synonyms: FY; FLJ22688; CPLANE3; NTD
Tractability: PROTAC: ubiquitination databases record sites on it.
Gene: Protein-coding gene on chromosome 19 (49,806,866 to 49,817,376, reverse strand). Ensembl gene ENSG00000010361.
Subcellular location: Cytoplasm; Cytoplasm, cytoskeleton; Cytoplasm, cytoskeleton, cilium basal body
Subcellular location (Human Protein Atlas): Cytosol
Pathways (Reactome):
Signal Transduction: Hedgehog 'off' state
Gene Ontology:
Molecular function: protein binding; phosphatidylinositol binding
Biological process: negative regulation of cell migration; neural tube closure; non-motile cilium assembly; positive regulation of cilium assembly; cilium assembly; embryonic body morphogenesis; embryonic skeletal system morphogenesis; establishment of planar polarity; hair follicle development; intraciliary transport; negative regulation of canonical Wnt signaling pathway; negative regulation of cell population proliferation; negative regulation of neural crest formation; neural tube development; regulation of cilium assembly; regulation of smoothened signaling pathway; vesicle-mediated transport
Cellular component: extracellular exosome; cilium; cytoplasm; cytoskeleton
Genetic constraint (gnomAD): Loss-of-function variants: 34 observed, 39.49 expected, observed/expected ratio (o/e) 0.86, 90% interval 0.65 to 1.15. The upper end of that interval is the gene's LOEUF score, 1.15, which puts it in group 5 of 6, group 1 being the genes least tolerant of losing a copy. Missense variants: 539 observed, 523.79 expected, observed/expected ratio (o/e) 1.03, 90% interval 0.96 to 1.11. Synonymous variants: 274 observed, 240.27 expected, observed/expected ratio (o/e) 1.14, 90% interval 1.03 to 1.26.
Homologues: Orthologues: chimpanzee FUZ (100% identical), macaque FUZ (98% identical), pig FUZ (89% identical), mouse Fuz (86% identical), rat Fuz (85% identical), guinea pig FUZ (82% identical), dog FUZ (60% identical), tropical clawed frog fuz (50% identical), zebrafish fuz (44% identical), Drosophila melanogaster fy (28% identical).
Diseases named in the same sentence as FUZ in open-access papers:
FUZ is named in the same sentence as 18 diseases in open-access papers, as found by Europe PMC text mining. Sharing a sentence is not in itself a finding about the gene and the disease. The quoted sentences say what the papers report.
ciliopathy (3 papers, 2020 to 2026). A genetic disorder of the cellular cilia or the cilia anchoring structures, the basal bodies, or of ciliary function. "Here, we report a patient with ciliopathy with a novel homozygous missense variant in FUZ." (PMID 41952398, 2026). "It contains several proteins, such as INTU, FUZ, WDPCP, JBTS17 and RSG1 (REM2- and RAB-like small GTPase 1), whose genes are mutated in ciliopathies." (PMID 31562761, 2020).
lung carcinoma (2 papers, 2020 to 2023). "Within the lung, higher methylation and lower expression of FUZ has previously been associated with tumour promotion and poor prognosis in lung adenocarcinoma, a compelling finding given the known increased rate of lung cancer in PLWH." (PMID 37143066, 2023). "The FUZ-BNIP3 axis may be considered as one of a potential group involving FUZ and BNIP3 as highly expressed proteins and FUZ as a prognostic factor of overall survival in patients with lung cancer." (PMID 33207677, 2020). "FUZ stimulates EMT and promotes cell proliferation in lung cancer cell lines." (PMID 33207677, 2020).
spina bifida (2 papers, 2025). A congenital neural tube defect in which vertebrae are not fully formed. "Genetic factors including variations in some specific genes such as MTHFR, MTHFD1, MTRR, VANGL1, VANGL2, CELSR1, and FUZ, as well as variants in the T-locus on chromosome 6q have also been studied in the development of spina bifida and other spinal dysmorphisms." (PMID 39835283, 2025). "While GPR161 has been previously linked with the WNT pathway and the planar cell polarity effector FUZ in spina bifida, our experiments here demonstrate that GPR161-mediated HH pathway regulation controls cranial neural tube closure." (PMID 41417007, 2025).
Anophthalmia (1 paper, 2021). Absence of the globe or eyeball. "FUZ knockout (Fuz−/−) mice exhibit severe craniofacial anomalies, including cleft palate, a hypoplastic mandible, and anophthalmia." (PMID 34445520, 2021).
congenital heart defects (1 paper, 2021). "FUZ is one of the four endocytic trafficking protein genes (LRP2, FUZ, DCTN5, and MYH10) that are related to the ciliome (a proteome of cilia) and congenital heart defects." (PMID 34445520, 2021).
craniosynostosis (1 paper, 2022). Craniosynostosis is defined as the premature fusion of one or more cranial sutures leading to secondary distortion of skull shape resulting in skull deformities with a variable presentation. "In this study, we report the first craniosynostosis associated variant of FUZ and propose a novel function of FUZ during the later stages of cranial bone development, using a mouse model to demonstrate that loss of FUZ leads to excessive ossification." (PMID 34719684, 2022).
Hermansky-Pudlak syndrome (1 paper, 2020). Hermansky-Pudlak syndrome (HSP) is a multi-system disorder characterized by oculocutaneous albinism, bleeding diathesis and, in some cases, neutropenia, pulmonary fibrosis, or granulomatous colitis. "Using two contrasting evolutionary analyses, coevolution-based contact prediction and sequence conservation, we first identified the INTU/FUZ heterodimer as a novel member of homologous HerMon (Hermansky-Pudlak syndrome and MON1-CCZ1) complexes." (PMID 31562761, 2020).
laryngeal carcinoma (1 paper, 2021). Carcinoma that arises from the laryngeal epithelium. "Our data confirmed that RCN1, DNAJA2, LASP1 and IBSP were up-regulated while LAT2, FUZ, HOOK2 and DAPK2 were down-regulated in laryngeal cancer." (PMID 34976784, 2021). "However, no study has explored the function of FUZ in laryngeal cancer." (PMID 34976784, 2021).
myelomeningocele (1 paper, 2020). Myelomeningocele is the most severe form of spina bifida. "Similar to the cilia proteins associated with exencephaly, perhaps FUZ’s transport of DVL to the cilium can also influence neural tube closure in myelomeningocele subjects." (PMID 32970752, 2020). "The genes PORCN, DVL2, CDH2, FUZ are already suspected to play a role in NTD development from studies in animal models and in some cases humans, however the remaining thirteen genes reported here are new in their possible association with myelomeningocele." (PMID 32970752, 2020). "The gene FUZ on chromosome 19, whose mouse homolog Fuz is a PCP effector protein required for ciliogenesis by transporting DVL to the cilium, is also associated with myelomeningocele in the MA population." (PMID 32970752, 2020).
non-small cell lung carcinoma (1 paper, 2022). A group of at least three distinct histological types of lung cancer, including non-small cell squamous cell carcinoma, adenocarcinoma, and large cell carcinoma. "The role of FUZ in glucose metabolism, invasion, and metastasis of non-small cell lung cancer (NSCLC) is unclear." (PMID 35711836, 2022).
orofaciodigital syndrome (1 paper, 2024). Two syndromes of oral, facial, and digital malformations. "Herein, we describe two Indian patients carrying biallelic variants in FUZ with digital anomalies, orofacial cleft, short ribs and cardiac defects resembling orofaciodigital syndrome." (PMID 38702430, 2024). "Our findings underscore the association between biallelic loss of function variants in FUZ and skeletal ciliopathy akin to orofaciodigital syndrome." (PMID 38702430, 2024).
tumor (3 papers, 2015 to 2023). "Extensive research has been conducted on the role of FUZ in the nervous system, and recent studies have found that FUZ also plays an important role in tumor development." (PMID 35711836, 2022). "In vivo, FUZ knockdown can significantly inhibit tumor proliferation in the xenograft model, which was well identified by Micro-PET scan." (PMID 35711836, 2022). "Twenty candidate genes (84%) showed methylation in greater than 50% of primary tumor, including ADFP, FUZ, ZNF71, ENPP5, ZNF211, and ZNF14." (PMID 26544568, 2015).
cancer (2 papers, 2022 to 2024). A tumor composed of atypical neoplastic, often pleomorphic cells that invade other tissues. "Moreover, five genes, including CITED2, C8orf44‐SGK3, FUZ, P2RY1, and SIX2, were associated with carcinoma migration." (PMID 38363001, 2024).
skeletal dysplasia (1 paper, 2026). Any Mendelian diseases that affects growth and development of the skeleton. "Five patients of various types of skeletal dysplasia with biallelic FUZ variants have been reported to date, yet the gene-disease relationship has not been established." (PMID 41952398, 2026).
FUZ also shares sentences with these, for which no sentence is quoted: cleft palate (1 paper); emphysema (1); lung adenocarcinoma (1); male infertility (1).